PTPA (protein phosphatase 2 phosphatase activator)
Diseases named in the same sentence as PTPA in open-access papers (continued):
Sharing a sentence is not in itself a finding about the gene and the disease.
infection (continued). "Altogether, our results provide further evidence supporting that PtpA could be the bacterial factor that dephosphorylates hTFPα during infection, potentially affecting its mitochondrial localization or β-oxidation activity." (PMID 37424790, 2023). "The review summaries knowledge on pathogenic bacterial protein tyrosine phosphatases (PTPs) involved in infection process, such as: PTPA and PTPB from Staphylococcus aureus and Mycobacterium tuberculosis; SptP from Salmonella typhimurium; YopH from Yersinia sp." (PMID 36552605, 2022). "As the ΔptkA and ΔptpA strains demonstrated similar phenotypes in the macrophage infection, and because ptkA is the first gene in the ptpA operon, we checked whether ptkA deletion could have resulted in the loss of ptpA expression." (PMID 29317718, 2018). "PtpA, a secreted tyrosine phosphatase, may directly exclude the vacuolar-H+ATPase during infection, impairing acidification and phagosome maturation, while nucleoside diphosphate kinase A (NdkA) targets Rab7 activation." (PMID 24204276, 2013). "The work confirmed that PtpA may be a bacterial factor that dephosphorylates hTFPα during infection, potentially affecting its mitochondrial localization or lipid β-oxidation activity during infection." (PMID 39858789, 2024). "Furthermore, in a previous study, we demonstrated that S. aureus PtpA is significantly secreted in macrophages 18 h after infection that could correlate with a late decrease of SUMOylation involving PtpA at 24-h post-infection." (PMID 37819153, 2023). "Furthermore, marP::Tn was ∼25 times more attenuated than ptpA::Tn during a 5-day infection, suggesting that, in vivo, tolerance of the acidic lysosomal environment is a more significant determinant of mycobacterial growth than avoidance of phagosome-lysosome fusion." (PMID 27512905, 2016). "We found that the transcription of the target genes was elevated in cells infected with BCG ΔPtpA strain at 12 h post-infection, but was suppressed in cells infected with WT BCG or BCG (ΔPtpA + PtpA) strain." (PMID 28811474, 2017). "Additionally, M. tuberculosis secretes PtpA to dephosphorylate host protein GSK3 and suppresses caspase 3 during early infection to prevent host-cell apoptosis." (PMID 35576232, 2022). "Accumulating evidence suggests that PtkA has an important role in sensing and adapting to the dynamic environment during macrophage infection and should also be considered as a potential therapeutic target independent of PtpA." (PMID 33826491, 2021). "An alternative interpretation of our observations is that the infection of macrophages by MAP and the subsequent secretion of PtpA could impact macrophage phenotypes and modulate the immune response in a manner that varies with the level of clinical activity in RA." (PMID 39752467, 2025). "Since Mtb PtpA is delivered into macrophages during infection and its amino acid sequence is 37% identical to that of the human low-molecular-weight phosphotyrosine phosphatase HCPTPA, several previous studies have made efforts to identify the host substrates of Mtb PtpA." (PMID 27698396, 2016).
neurodegenerative disease (26 papers, 2014 to 2025). A disorder of the central nervous system characterized by gradual and progressive loss of neural tissue and neurologic function. "Additionally, there are other endogenous regulators, that include SET and PTPA, which may contribute to PP2A inhibition in neurodegenerative diseases." (PMID 29950985, 2018).
PTPA also shares sentences with these, for which no sentence is quoted: pancreatic cancer (43 papers); prostate carcinoma (43); leukemia (41); Insulin resistance (36); colorectal cancer (34); hepatocellular carcinoma (31); melanoma (29); glioblastoma (27); tauopathies (25); Cognitive impairment (24); colon carcinoma (23); diabetes (23); neuroblastoma (20); non-small cell lung carcinoma (18); glioma (17); acute myeloid leukemia (16); heart failure (13); triple-negative breast carcinoma (13); autoimmune disease (12); chronic myeloid leukemia (12); ovarian carcinoma (12); viral infection (12); Intellectual disability (11); multiple myeloma (11); multiple sclerosis (11); cardiac hypertrophy (10); hematological malignancies (10); lung adenocarcinoma (10); breast tumor (9); cervical carcinoma (9).
A further 249 diseases each share a sentence with PTPA in 9 papers or fewer.